CD24 (CD24 molecule)
Diseases named in the same sentence as CD24 in open-access papers (continued):
Sharing a sentence is not in itself a finding about the gene and the disease.
tumor (continued). "This dual role of CD24 in tumor progression and lymphangiogenesis underscores its significance as a potential therapeutic target for BC intervention." (PMID 40895068, 2025). "Our findings highlight the efficacy of CD24-guided delivery and demonstrate the translational potential of exploiting tumor metabolic vulnerabilities through environment-responsive nanotherapeutics." (PMID 41281650, 2025). "Via the CD24 or β‐catenin pathway, Daxx plays a tumor suppressor role by regulating the biological processes in human tumor samples and in vitro." (PMID 40130316, 2025). "Taken together, these data suggest that CD24+ tumor cells are more sensitive to HER2 inhibition-induced proliferation arrest, while CD44-expressing tumor cells display a survival advantage under therapeutic pressure." (PMID 40430044, 2025). "Neither tissue showed appreciable expression of HER2 or MUC16; however, both displayed levels of CD24 that were detectable yet significantly below those evident in the tumor samples." (PMID 40841152, 2025). "The CD24/Siglec-10 axis significantly inhibits tissue damage-induced immune response and mediate immune escape of tumor cells." (PMID 40486886, 2025). "CD24-mediated targeting significantly enhanced drug accumulation at the tumor site, reduced NADPH levels, and triggered cystine-induced disulfidptosis." (PMID 41281650, 2025). "Apart from its essential role in regulating tumor progression and immune evasion, CD24 is found to be involved in chemotherapy resistance." (PMID 40486886, 2025). "Concurrently, CD24 facilitates the immune evasion of tumor cells by recognizing Siglec‐G/10 on macrophages, P‐/E‐selectin on endothelial cells, and L1CAM on lymphocytes." (PMID 41354057, 2025). "CD24 is a “don’t eat me” signal that has inhibitory effects in tumor immunity by binding to Siglec-10 on macrophages." (PMID 40486886, 2025). "qPCR analysis revealed significant upregulation of CD24 in C. sinensis-infected HCC tumor tissues compared with adjacent tissues." (PMID 40830893, 2025). "On the one hand, CD24, a cancer stemness marker, can be expressed in tumor cells and play a suppressive role in tumor immunity as a phagocytic inhibitor when bound to macrophages via Siglec-10." (PMID 40076927, 2025). "CD24 can act as a specific cancer biomarker, providing a theoretical basis for targeted therapy of tumor cells and serving as a reference for prognosis and recurrence monitoring." (PMID 40486886, 2025). "This shift, coupled with tumor cells overexpressing the anti‐phagocytic signal CD24, collectively fosters an immunosuppressive and tumor‐promoting microenvironment." (PMID 40904700, 2025). "CD44+/CD24-/low mammospheres are the main component of residual cells after docetaxel treatment and can lead to tumor recurrence in breast cancer." (PMID 39919692, 2025). "Crucially, our study establishes a direct link between CD24 and the induction of a senescence-like phenotype in tumor cells." (PMID 40777020, 2025). "When it comes to cytoplasmic CD24, several reports suggest contradicting roles for cytoplasmic CD24 in tumor progression." (PMID 39136818, 2025). "Exosome-mimetic vesicles (EMs) displaying anti-CD24 nanobodies were then fabricated via sequential extrusion and validated in vitro and in vivo for their tumor-targeting capabilities." (PMID 41281650, 2025). "To realize tumor-selective accumulation of GOx and cystine, we engineered a CD24-targeted nanovesicle platform (Cys-hMnO2@GOx@EM-CD24)." (PMID 41281650, 2025). "Epigenetically, non-coding RNAs (ncRNA) can crosslink tumor cells with tumor microenvironment through extracellular vesicles, etc., thereby regulating the expression of CD24." (PMID 40486886, 2025). "Tumor-expressed CD24 promoted immune evasion by interacting with the inhibitory receptor sialic-acid-binding Ig-like lectin 10 (Siglec-10), which is expressed by M2-like tumor-associated macrophages (TAMs)." (PMID 40770672, 2025).
tumor (continued). "For example, the downregulation of long non-coding RNA (lncRNA) H19 helps to improve the expression of CD24 on the cell surface and increase the invasion ability of tumor." (PMID 40486886, 2025). "In BC and other malignancies, CD24 is often overexpressed, contributing to immune evasion, tumor cell proliferation, invasion, and metastasis." (PMID 40895068, 2025). "In this study, we developed an extracellular vesicle liquid biopsy to identify miRNA biomarkers packaged within HER2+ and CD24+ plasma EVs for the classification of malignancy in women with BI-RADS 4 breast lesions." (PMID 40405296, 2025). "CD24 also plays a crucial role in the tumor growth, cellular proliferation, epithelial-mesenchymal transition, angiogenesis, invasion, metastasis, promoting Immune invasion and acquisition of drug resistance in TNBC." (PMID 40297849, 2025). "CD24 plays a crucial role not only in promoting tumor progression and metastasis but also in modulating macrophage-mediated anti-tumor immunity." (PMID 40783744, 2025). "We demonstrated that SETD1B, driven by MAZ, enhances stem characteristics by promoting anchorage-independence, cellular adhesion, tumor sphere formation, and growth via the surface glycoprotein CD24." (PMID 40860182, 2025). "The overall proportion of CD24+CD271+ cells in the two tumours that contain them (one from each dataset) is similar to that in the CHL1 cell line." (PMID 40754577, 2025). "Given the complexity of the liver immune microenvironment, we systematically evaluated the correlation between CD24 expression and the tumor immune microenvironment characteristics using the TIMER2.0 database." (PMID 40830893, 2025). "CD24+ cells in OC have been observed to exhibit anoikic resistance, enhanced tumor growth, colony formation, an EMT phenotype and stem-like properties, including self-renewal." (PMID 40136652, 2025). "On the other hand, CD24 affects the function of the immune system, promotes a series of immunosuppression-related responses, helps tumor cells escape immunity, and mediates radiotherapy and chemotherapy resistance." (PMID 40486886, 2025). "CD24, as a cancer stem cell marker, has recently been confirmed to be a phagocytosis checkpoint and highly expressed on tumor cells." (PMID 40835598, 2025). "Overall, the CD24-mediated pathways played a role in both innate and adaptive immunity, inducing chemoradiotherapy resistance in tumor cells, and the specific mechanisms still require further exploration." (PMID 40486886, 2025). "Identified oncofetal RBPs were most prevalent in EMT-like, proliferative, neuronal-like, CD24+, and invasive tumor cell clusters." (PMID 41444249, 2025). "The latest research indicates that the genetic ablation of CD24 and Siglec-10 is an effective method for targeting tumor cells and enhancing the phagocytic action of macrophages." (PMID 40486886, 2025). "Consistent with the C.sinensis-positive tumor tissue changes, CD24 was significantly upregulated in CsESPs-treated HCC cells." (PMID 40830893, 2025). "Cells co-expressing PROM1 and CD24 have been isolated from ccRCC tumors as a small overall component of the tumor but with progenitor properties." (PMID 40558504, 2025). "Secretion of CXCL8 by tumor cells modulated the expression of plasma cell CD24, which ultimately attenuated the activation of B cells into plasma cells." (PMID 40510161, 2025). "Additional assays demonstrated that inclusion of SM1Aexo and MRX-2843 further enhanced anti-tumor activity, as evidenced by increased tumor cell phagocytosis and effective blockade of CD24." (PMID 41294574, 2025). "CD24 mediates radiotherapy and chemotherapy resistance by affecting the intrinsic functions of tumor cells and promoting tumor occurrence and progression." (PMID 40486886, 2025). "Further studies should examine the expressions of CD47 and CD24 at the transcriptional levels to further understand the mechanism of CD47/SIRPα and CD24/Siglec‐1 pathways in the anti‐tumor immune response." (PMID 41354057, 2025).
tumor (continued). "CD24 was identified as a marker of cancer stem cells in various human malignancies and is involved in tumor metastasis and invasion." (PMID 41354057, 2025). "In all tested tumor samples, the expression profile of CD24, PD-L1, and MHC-I & II showed a broad spectrum of expression in the range between 0->90% in all tested BC subentities." (PMID 40148963, 2025). "In all subgroups examined, CD24 expression remained consistently higher in tumor tissue than in normal liver tissues." (PMID 40830893, 2025). "Tumor cells expressing high levels of self-markers, such as the CD24/Siglec-10 signal axis, phosphorylate ITIMs (immune receptor tyrosine-based inhibitory motifs), thereby activating downstream pathways and releasing anti-phagocytic signals." (PMID 40260303, 2025). "Mechanistically, CsESPs upregulates E2F1, which subsequently activates CD24 transcription, ultimately promoting tumor cell proliferation while suppressing apoptosis." (PMID 40830893, 2025). "CD44, CD24, Prominent-1 (CD133), and EpCAM are selectively expressed or elevated in CSCs, and are directly associated with tumor recurrence." (PMID 40069421, 2025). "In the context of oncogenesis, CD24 is frequently overexpressed and contributes critically to tumor progression by promoting cancer cell proliferation, migration, invasion, metastasis, and the maintenance of stem-like properties." (PMID 40777020, 2025). "Next, to further enhance macrophage activity, the engineered macrophages were modified to overexpress SM1Aexo, which competitively blocks CD24 on the surface of tumor cells, thereby promoting greater phagocytosis by TAMs." (PMID 41294574, 2025). "Immunohistochemistry of tumor tissues showed lower CD24 protein levels in LV-pre-miR-10a expressing tumors and higher levels in LV-anti-miR-10a expressing tumors." (PMID 41551164, 2025). "A pan‐cancer analysis of CD24/CD47 expression from TCGA showed an extensive overexpression across 31 tumor entities compared to normal tissues." (PMID 41354057, 2025). "Genetic deletion and therapeutic inhibition of either CD24 or Siglec-10, as well as blocking their interaction using mAbs, can augment the phagocytic capacity of macrophages in CD24-expressing human tumours and promotes tumour-specific responses." (PMID 40385641, 2025). "The one tumour that expressed CD24 was also the only tumour with a large number of cells expressing CD271." (PMID 40754577, 2025). "In the majority of cancer entities, tumor cells exert a pronounced inhibitory effect on infiltrating immune cells via various membrane-bound checkpoint molecules like PD-L1 or CD24." (PMID 40649953, 2025). "The blockade of CD24/Siglec-10 signaling was found to promote the macrophage-mediated phagocytosis of CD24-expressing tumors and effectively inhibit tumor growth." (PMID 40380196, 2025). "Firstly, the precise targeting of the drug affects its efficacy, and since CD24 is expressed in many tissues, further exploration is needed to achieve accurate targeting of CD24 in tumor tissues." (PMID 40486886, 2025). "Two antiphagocytic (“don't eat me”) signals that allow tumor immune evasion have been discovered, including CD24 and CD47." (PMID 41354057, 2025). "The plasma cells were found to be affected by CXCL8 secreted by the tumor cells, and the predicted target gene was CD24." (PMID 40510161, 2025). "Following adjustments for tumor purity, our analysis confirmed a significant correlation between CD24 expression and most established markers representative of these immune cell types." (PMID 40830893, 2025). "Hurt demonstrated that CD44+CD24- prostate stem-like cells isolated from the LNCaP cell line exhibited tumor-forming potential following the injection of as few as 100 cells into NOD/SCID mice." (PMID 40136652, 2025).
tumor (continued). "The significantly higher presence of CD19lo CD38hi CD24- CD27lo IgD- antibody secreting plasma cells in the tumour compared to blood, and the contrasting abundance of naïve, memory and plasmablast cells in circulation was a key finding from our work." (PMID 40904468, 2025). "CD24 also acts on integrin subunits, promoting the binding of tumor cells to extracellular matrix components such as collagen, thereby promoting tumor cell deposit and migration." (PMID 40486886, 2025). "The one CD24+ tumour did however contain CD24+CD271+ cells, at 7% of the total malignant cell population." (PMID 40754577, 2025). "During transcription, hypoxia-inducible factors (HIFs) are induced as transcription factors of CD24 when oxygen supply is limited and oxygen content in the tumor microenvironment is low." (PMID 40486886, 2025). "Tumor cells were defined as EpCAM+ CD90− CD140a− CD45− CD33− CD14− and further analyzed for the expression of CD24 and CD44, two markers associated with tumor aggressiveness and stem-like features." (PMID 40877861, 2025). "CD24/Siglec-10 signaling (inhibitory receptor sialic-acid-binding Ig-like lectin 10) subverts the immune surveillance of tumor cells." (PMID 40380196, 2025). "Individual differences of the stem cell associated markers CD24 and CD44, as well as MHC- and PD-L1 expression on tumor cells of HNSCC patients were detectable using flow cytometry." (PMID 40860824, 2025). "Although NGF-differentiated PC12 neuron-like cells exhibit lower CD24 than tumor cells and reduced sensitivity to Cys-hMnO2@GOx@EM-CD24, neuro-safety still requires further validation, particularly in primary sympathetic neuron models and in juvenile mice." (PMID 41281650, 2025). "The patients with a low CD3+ TIL density and a high CD24 expression in tumor cells emerged as a subgroup with the shortest survival, with median DFS and MFS of 2.6 and 3.9 years, respectively." (PMID 40647395, 2025). "CD24 binds to P-selectin, reducing tumor cells adhesion, enhancing endothelial rolling, and promoting metastasis." (PMID 40486886, 2025). "In-depth studies found that CD24 affects the behavior of tumor cells and the function of immune cells, induces the resistance to radiotherapy and chemotherapy, and promotes the progression and poor prognosis of cancer." (PMID 40486886, 2025). "CD24/Siglec-10 signaling disrupts tumor cell immune surveillance, and pathway blockade promotes macrophage phagocytosis of CD24-expressing tumor cells, effectively inhibiting tumor growth." (PMID 41417432, 2025). "First, CD24 expression showed progressive upregulation across advancing tumor stages (stages 1–3) compared with normal liver tissue." (PMID 40830893, 2025). "Studies have confirmed that the depletion of either CD24 or Siglec-10 can reinvigorate the phagocytosis of TAMs and reduce tumor growth." (PMID 41341850, 2025). "The targeting of CD24 offers significant benefits in cancer therapy due to its selective expression on tumor cells and its role in modulating immune escape mechanisms." (PMID 38881902, 2024). "The activation of these α3β1 and α4β1 integrins through CD24 expression enhances tumor invasion and metastasis by encouraging cell adhesion to various extracellular components, including fibronectin, collagens I and IV, and laminin." (PMID 38881902, 2024). "In BRCA, the interaction of sialylated CD24 on the tumor cell surface with Siglec-E on macrophages forms the CD24-Siglec-E axis, which enhances immunosuppression and promotes tumor growth." (PMID 39791710, 2024). "CD24 is one of P-selectin ligands, which is involved in the proliferation, invasion and metastasis of tumor cells through specific binding to P-selectin." (PMID 38914670, 2024). "Recent studies have indicated that surface CD24 in tumours is a novel antiphagocytic protein that interacts with sialic-acid-binding Ig-like lectin 10 (Siglec10) on macrophages." (PMID 38702326, 2024).
tumor (continued). "YAP is shown to regulate CD24 expression by binding to TEAD and activating the CD24 promoter, aiding tumor cell evasion from macrophage clearance." (PMID 39415846, 2024). "HE staining further indicated that the cell nuclei in the CD24 knockdown subcutaneous tumor tissue were relatively shallow and the cell arrangement was relatively regular." (PMID 38914670, 2024). "ZNF460 binds to prediction sites in the CD24 promoter region, and ZNF460 leads to significant induction of CD24 promoter activity, so the up-regulation of CD24 in BC is due in part to CD24 activation during tumor progression." (PMID 38914670, 2024). "CD24 enhances the mobility of tumor cells through the activation of integrin subunits (notably α3β1 and α4β1), which support tumor cell adhesion to fibronectin and various extracellular matrix elements, including collagen types I and IV, as well as laminin." (PMID 38881902, 2024). "Mechanistically, YAP regulates CD24 expression by interacting with TEAD and binding the CD24 promoter to initiate transcription, which facilitates tumor cell escape from macrophage-mediated immune attack." (PMID 38168654, 2024). "Secondly, targeting CD24 can disrupt the “don’t eat me” signal that tumor cells emit to avoid phagocytosis by macrophages." (PMID 38881902, 2024). "During tumor‐killing assays, anti‐CD24 neutralizing antibodies significantly rescued the Siglec‐G‐mediated inhibition of CD8+ T cells cytotoxicity." (PMID 39373395, 2024). "There is an urgent need for more targeted anti-CD24/Siglec-10 mAbs that can effectively target tumor-specific forms of CD24/Siglec-10 and glycosylation variations." (PMID 38279998, 2024). "For example, the tumour cell expressed genes CD24, CLU, and SLPI35–37 and the infiltrating cell expressed genes GPNMB, MGP, GPX3, and MFAP438–41 have all been previously associated with poor prognosis and chemotherapy resistance in HGSOC." (PMID 38570491, 2024). "The proteins PLK1, SPIB, and CD24 show darker staining in tumor tissues, while NTRK3 and EDA2R exhibit lighter staining in tumor tissues." (PMID 39596658, 2024). "The role of the CD24-Siglec-10 axis on suppression of anti-tumor immunity highlights its potential as a theranostic target in cancer treatment." (PMID 40836974, 2024). "CD24, an emerging class of cancer immunotherapies that modulate immune responses within the tumor microenvironment by targeting the CD24 protein." (PMID 39013849, 2024). "In this study, unexpectedly, we found YAP directly activated transcription of the “don’t eat me” signal CD24, and played an important role in driving tumor cells to avoid phagocytosis by macrophages." (PMID 38168654, 2024). "For example, the cell-surface protein CD24 shows contradictory results regarding its role in tumor progression." (PMID 39225101, 2024). "Depletion of YAP downregulated CD24 expression and markedly promoted the phagocytosis of tumor cells by macrophages." (PMID 38168654, 2024). "Meanwhile, we detected the binding of endogenous Siglec-E to CD24 in 4T1 tumor tissues by fluorescence immunohistochemistry using anti-Siglec-E antibodies." (PMID 39791710, 2024). "CD24 on tumor cells is known to interact with Siglec-10 on innate immune cells to inhibit engulfment." (PMID 38168654, 2024). "Numerous studies have suggested that increased cluster of differentiation 24 (CD24) expression in tumours predicts poor prognosis." (PMID 38702326, 2024). "A significant increase in human CD44 mRNA expression levels was observed in tumor tissues of mice xenotransplanted with CD24−/CD44+‐breast CSCs as compared to sham control." (PMID 38522013, 2024).